CFTR (CF transmembrane conductance regulator)
Diseases named in the same sentence as CFTR in open-access papers (continued):
Sharing a sentence is not in itself a finding about the gene and the disease.
allergic bronchopulmonary aspergillosis (11 papers, 2012 to 2025). Allergic bronchopulmonary aspergillosis (ABPA) is a rare immunologic pulmonary disorder caused by hypersensitivity to Aspergillus fumigatus, clinically manifesting with poorly controlled asthma and recurrent pulmonary infiltrates. "In conclusion, the results of our in vivo studies show that loss of normal CFTR function increases the inflammatory response in the lung, in both acute and allergic aspergillosis models." (PMID 39903773, 2025). "We employed a repeat challenge model of allergic aspergillosis in which WT and CFTR-/- mice were intranasally infected with 2 x 105 CEA10 A. fumigatus conidia daily for 14 days." (PMID 39903773, 2025). "These are transplantation, CFTR modulators, Pseudomonas aeruginosa, Burkholderia cepacian, and allergic bronchopulmonary aspergillosis." (PMID 36983631, 2023).
intestinal cancer (11 papers, 2020 to 2025). "Activation of NF-κB signaling pathways has been observed downstream of CFTR deficiency in several tissues and cancers including in esophageal and intestinal cancers." (PMID 35743652, 2022). "CFTR has been proposed a tumor suppressor protein and CFTR deficiency is implicated in airway and intestinal cancer progression and poor prognosis." (PMID 33935699, 2021). "The elevated risk of CRC in people with CF is not yet completely understood but CFTR dysfunction in the intestine is known to be associated dysbiosis of the gut microbiome and chronic inflammation, two factors that have been associated with the development of intestinal cancer." (PMID 40066329, 2025). "These CFTR KO mice were then introgressed into the ApcMin mouse model of intestinal cancer, resulting in the significant enhancement of tumorigenesis throughout the intestinal tract compared with ApcMin CFTR wildtype littermate control mice." (PMID 35743652, 2022). "To determine any putative effect of AAT on the CFTR levels, we initially used human intestinal cancer epithelial cell line T84, highly expressing CFTR, and historically used in experiments to study CFTR levels." (PMID 33946490, 2021). "In intestinal cancer, CFTR has been proposed as a tumor suppressor gene that regulates other tumor-related genes." (PMID 32182826, 2020). "Finally, CFTR’s role as a tumor suppressor in intestinal cancer was confirmed in an intestinal specific CFTR knockout mouse model." (PMID 35743652, 2022). "CFTR tumor suppressor activity has been previously identified in several cancers including breast, prostate, NSCLC, and intestinal cancer." (PMID 32182826, 2020). "CFTR, also called ABCC7, is a cyclic adenosine mono-phosphaste-regulated anion channel that has been suggested to be a tumor suppressor gene in human intestinal cancer." (PMID 32584883, 2020).
polycystic kidney disease (11 papers, 2013 to 2024). A usually autosomal dominant and less frequently autosomal recessive genetic disorder characterized by the presence of numerous cysts in the kidneys leading to end-stage renal failure. "The first consideration is that CFTR inhibition might be a useful approach for human pathologies, such as polycystic kidney disease (PKD)." (PMID 37104011, 2023). "Moreover, it has also been postulated that inhibitors of CFTR may slow down the progression of polycystic kidney disease." (PMID 31488014, 2019). "More recently, in an effort to identify new inhibitors of CFTR, the compound PPQ-102 was demonstrated to inhibit CFTR conductance and to prevent expansion of cysts in a kidney organ culture model of polycystic kidney disease." (PMID 28620305, 2017). "On the other hand, the possibility of using small molecules to inhibit hyper-activated CFTR in diseases like secretory diarrhea and polycystic kidney disease has not been as rigorously exploited." (PMID 39107303, 2024).
bronchitis (10 papers, 2006 to 2025). An acute or chronic inflammatory process affecting the bronchi. "It had been previously shown that the bronchitis severity is significantly associated with CFTR activity in the nasal airway, lungs, and even extrapulmonary tissues." (PMID 38578805, 2024). "A pilot study of ivacaftor benefited CFTR activity in some of the patients tested, and was associated with improved bronchitis symptom scores." (PMID 28923049, 2017). "For bronchitis, Progeni identified the cystic fibrosis transmembrane conductance regulator (CFTR) with the third-highest prediction score." (PMID 38578805, 2024). "Roflumilast effectively rescues CFTR-mediated chloride transport in vivo, further implicating CFTR activation as a mechanism through which roflumilast benefits patients with bronchitis." (PMID 28923049, 2017). "Whilst stratification of bronchial infection subgroups was adequate, stratification of specific CFTR genotypes required a frequency based approach to search for significant associations." (PMID 17137500, 2006). "As such, this mouse model of cigarette smoke exposure is highly informative for evaluating the effects of roflumilast on CFTR-mediated ion transport in vivo, paving the way for further investigation with more complex animal models that exhibit bronchitis upon smoke exposure." (PMID 28923049, 2017). "Roflumilast functioned as a CFTR activator, reversed CFTR dysfunction and increased intestinal fluid in mice in a CS exposure-dependent manner, and benefited COPD patients with bronchitis." (PMID 36226596, 2023). "In addition, the relationship between lower airway CFTR activity and small airway mucus clearance is unknown as is the effect of CFTR dysfunction on clinical phenotype (e.g. exacerbation frequency, lung function, and symptoms of bronchitis and dyspnea)." (PMID 22768130, 2012). "In addition, reflecting the short duration of the study mice exhibiting CFTR dysfunction do not recapitulate overt bronchitis reminiscent of COPD." (PMID 32192506, 2020).
chronic lung infection (10 papers, 2010 to 2024). "In the lung and upper airways, dysfunction of CFTR leads to the formation of thick mucopurulent secretions and impaired mucociliary clearance, predisposing individuals to the establishment of chronic lung infections, mostly by Staphylococcus aureus and Pseudomonas aeruginosa." (PMID 36979360, 2023). "In contrast, studies using cells from CFTR deficient animals (that have not developed chronic lung infections and inflammation) and human CF macrophages cultured in vitro indicate that lack of CFTR activity causes macrophages to mount overly robust inflammatory responses." (PMID 33013356, 2020). "The development of mouse models with Cftr deletion or with the F508del mutation have been fundamental for experimentally studying the role of CFTR in bone biology without confounders such as chronic lung infection and/or chronic malnutrition." (PMID 36979360, 2023).
cystic fibrosis-related diabetes (10 papers, 2020 to 2026). Cystic fibrosis-related diabetes is a form of diabetes that occurs frequently in individuals with cystic fibrosis. "CFTR is only expressed in the pancreatic ductal epithelial cells in the human pancreas, and defective CFTR function indirectly causes impaired endocrine pancreatic function, resulting in cystic fibrosis-related diabetes (CFRD)." (PMID 34202364, 2021). "Cystic fibrosis-related diabetes was detected in two patients with CFTR mutations." (PMID 33663443, 2021). "Knockout (KO) ferrets with the cystic fibrosis transmembrane conductance regulator (CFTR) exhibit distinct phases of dysglycemia and pancreatic remodeling prior to cystic fibrosis-related diabetes (CFRD) development." (PMID 39641365, 2024). "In summary, we believe that CFTR affects the pancreas functionality and the insulin-responsive tissues; both contribute to cystic fibrosis-related diabetes (CFRD)." (PMID 33659254, 2021).
depression (10 papers, 2015 to 2025). "This decline in lung function varies with the presence of CFTR mutation, age at diagnosis, presence of PI, environmental pollution, nutritional status, adherence to treatment, comorbidities (DM, depression, osteopenia, and chronic infection), and sex." (PMID 25592785, 2015). "Therefore, a corresponding link between loss of CFTR function and depression and anxiety needs to be examined in order to uncover potential therapies thereby improving the quality of life for CF patients." (PMID 33004910, 2020). "No other clinical factors we examined (age, gender, FEV1pp, CFTR variant, prior diagnosis of depression, or baseline GAD‐7 ≥ 5) were associated with clinically significant worsening of PHQ‐9 score after E/T/I initiation." (PMID 39210645, 2024). "No other clinical factors (age, gender, FEV1pp, CFTR variant, prior diagnosis of depression, or baseline PHQ‐9 ≥ 5) were associated with clinically significant worsening of GAD‐7 score after E/T/I initiation." (PMID 39210645, 2024). "There were six (7.1%) CFTR-carrier women with a history of depression, compared to eight (8.8%) in the non-carrier group." (PMID 35886548, 2022).
Insulin resistance (10 papers, 2017 to 2025). Increased resistance towards insulin, that is, diminished effectiveness of insulin in reducing blood glucose levels. "However, little is known regarding the mechanism of CFTR loss-of-function in insulin resistance." (PMID 33659254, 2021). "On the other hand, improved calorie intake and intestinal absorption, due to CFTR modulator therapy, leads to weight gain and, as a result, increased insulin resistance." (PMID 36980112, 2023). "As Akt2 is an essential kinase in insulin resistance, we investigate the phosphorylation of Akt2 in CFTR–/– mice." (PMID 33659254, 2021). "However, the variability in results across studies suggests that the relationship between CFTR function and glucose metabolism is complex and influenced by multiple confounding factors, including insulin resistance, disease stage, and treatment duration." (PMID 41332894, 2025). "Herein, we found that CFTR knockout mice exhibited insulin resistance and glucose tolerance." (PMID 33659254, 2021). "Furthermore, the potential enhancement of the caloric intake and intestinal absorption through CFTR modulator therapy may lead to weight gain, consequently contributing to elevated insulin resistance." (PMID 38136081, 2023). "The modulation of the CFTR protein using the ELX/TEZ/IVA combination may positively influence the membrane transport of glucose transporter 4 (GLUT4) and ameliorate insulin resistance." (PMID 38136081, 2023). "Modulating CFTR by ELX/TEZ/IVA could positively influence GLUT4 membrane transportation and improve insulin resistance." (PMID 35529332, 2022).
lung adenocarcinoma (10 papers, 2012 to 2025). A carcinoma that arises from the lung and is characterized by the presence of malignant glandular epithelial cells. "In contrast, the association of increased CFTR expression with improved outcomes in lung adenocarcinoma was confirmed in two independent cohorts." (PMID 35715537, 2022). "The association between reduced CFTR expression and outcomes in patients with lung adenocarcinoma was among the most significant in our data." (PMID 35715537, 2022). "The association between low CFTR levels and reduced survival in lung adenocarcinoma was confirmed in two independent cohorts of 246 patients with a history of smoking (logrank P = 0.0021, hazard ratio [HR], 0.49) and 143 never-smokers (logrank P = 0.0023, HR 0.31)." (PMID 35715537, 2022). "Our results demonstrate that ivacaftor significantly reduced the proliferation of lung adenocarcinoma cells, corroborating that CFTR activity is mechanistically involved in cancer pathogenesis and acts as a pharmacologically targetable tumor suppressor." (PMID 35715537, 2022). "Further in vitro experiments using naturally CFTR expressing lung adenocarcinoma cells showed that treatment with CFTR potentiators significantly reduced proliferation at therapeutically relevant concentrations." (PMID 35715537, 2022). "The aim of this study is to investigate impacts of CFTR on the malignant features of lung adenocarcinoma A549 cells." (PMID 29526175, 2018). "This study was conducted to evaluate the effects of dexamethasone treatment on CFTR expression in a serous cell model, Calu-3 cells (lung adenocarcinoma), and to understand the mechanisms involved in such regulation." (PMID 23272037, 2012). "Combined, the presented study identified CFTR expression as a prognostic marker for survival in lung adenocarcinoma and suggests that stimulation of CFTR function using safe concentrations of ivacaftor might provide a novel strategy to reduce tumor cell proliferation." (PMID 35715537, 2022). "In our study, we found the characteristic genes that affected lung adenocarcinoma through the propionate pathway included LDHA, KYNU, SLC2A1, CFTR, and MAOB." (PMID 41003841, 2025). "The −33 kb CRE, which to date is functionally uncharacterized, is only observed in 16HBE14o− cells and not in the CFTR‐expressing lung adenocarcinoma cell line Calu3 or primary human bronchial epithelial cells." (PMID 37269165, 2023). "Notably, because the most commonly used and highly proliferative lung adenocarcinoma cell line A549 does not express CFTR, we used Calu-3 cells, which exhibit natural CFTR expression and thus do not require CFTR overexpression, as in previous studies." (PMID 35715537, 2022).
non-small cell lung carcinoma (10 papers, 2017 to 2023). A group of at least three distinct histological types of lung cancer, including non-small cell squamous cell carcinoma, adenocarcinoma, and large cell carcinoma. "Moreover, DNA methylation and mutations of CFTR have been identified in non-small cell lung cancer (NSCLC), which is a common lung malignancy characterized by poor long-term survival that is mainly due to metastasis and tumour relapse." (PMID 30764828, 2019). "Methylation of CFTR gene was also reported to be high (30.2%) in non-small cell lung carcinoma (NSCLC) tissue samples and related to significantly lower CFTR expression in these samples in comparison to normal lung tissue." (PMID 32365523, 2020).
adenoma (9 papers, 2018 to 2026). A neoplasm arising from the epithelium. "The risk of CRC in adults with CF is 5–10 times greater compared to the general population and it is estimated that 25% of patients with CF will develop advanced adenomas, with a risk also extended to carriers of CFTR mutations." (PMID 33672345, 2021). "Linaclotide-stimulated bicarbonate secretion was eliminated by down-regulated in adenoma (DRA, SLC26A3) inhibition during loss of CFTR activity." (PMID 37205513, 2024). "Two anion transporters mediate this process at the apical membrane of the colonic epithelium: the chloride/bicarbonate exchanger SLC26A3 (also known as down‐regulated in adenoma, DRA) and the cystic fibrosis transmembrane conductance regulator (CFTR)." (PMID 41498431, 2026).
glioma (9 papers, 2016 to 2026). A benign or malignant brain and spinal cord tumor that arises from glial cells (astrocytes, oligodendrocytes, ependymal cells). "To further determine the involvement of CFTR in glioma cell viability, we did gain and loss of function studies in U87 and SW1088 cells." (PMID 32463592, 2020). "This combined network linked both PRKG1 and CFTR to genes already known to be of importance in glioma biology such as PDGFRA, met, and TGFβ2, amongst others." (PMID 27564115, 2016). "Similarly, we found heterozygous CFTR GVs to be significantly more frequent in glioma patients with presumed tumor predisposition compared to controls, suggesting a link to glioma risk." (PMID 41546701, 2026). "Second, the amplification of CFTR, which has been associated with decreased tumour proliferation and better survival in gliomas, may also have exerted a protective influence." (PMID 41573648, 2025). "In-vitro study demonstrates that CFTR suppresses apoptosis of glioma cells; inhibition of CFTR function or expression suppresses the glioma cell viability, whereas overexpression of CFTR shows an opposite impact." (PMID 36935741, 2023). "We treated glioma cells with CFTRinh‐172 (inh172) and found that CFTR inhibitor repressed cell viability in all glioma cell lines tested." (PMID 32463592, 2020). "The immunofluorescent staining result showed that CFTR was mostly expressed in the cytoplasm of glioma cells." (PMID 32463592, 2020). "Our results clearly indicate that CFTR promotes glioma development via Akt/Bcl2‐mediated anti‐apoptosis pathway." (PMID 32463592, 2020). "Taken together, based on our findings and previous study, it is plausible that CFTR promotes glioma progression via up‐regulation of Akt/Bcl2‐mediated anti‐apoptosis pathway." (PMID 32463592, 2020). "Two different CFTR antibodies targeting either C terminus (CFTR‐C) or N‐terminus (CFTR‐N) were used to detect CFTR protein in glioma cell lines." (PMID 32463592, 2020). "Altogether, our study has revealed a mechanism by which CFTR promotes glioma progression via up‐regulation of Akt/Bcl2‐mediated anti‐apoptotic pathway, which warrants future studies into the potential of using CFTR as a therapeutic target for glioma treatment." (PMID 32463592, 2020). "In the current study, we have shown that PI3K/Akt pathway mediates the effect of CFTR on apoptosis regulation in glioma cells." (PMID 32463592, 2020). "Our results showed that knockdown of CFTR significantly reduced cell viability in SW1088, while overexpression of CFTR significantly enhanced cell viability in U87, indicating CFTR promotes glioma cell viability." (PMID 32463592, 2020). "While the expression levels of mature CFTR were similar in all glioma cell lines, the expression levels of immature and total CFTR were significantly higher in SW1783 and SW1088." (PMID 32463592, 2020). "In our study, we have found that CFTR up‐regulates Bcl2 more than Bax via PI3K/Akt pathway, thus decreases the ratio of Bax/Bcl2 and makes the glioma cells less susceptible to apoptotic signals." (PMID 32463592, 2020). "Suppression of CFTR channel function or knockdown of CFTR suppresses glioma cell viability whereas overexpression of CFTR promotes it." (PMID 32463592, 2020). "The DICER1 and most of the SDHA and CFTR GV carriers developed glioma after the age of 65 years." (PMID 41546701, 2026). "Other gene functions implicated in glioma risk in this study include signal transduction (e.g. EGFR), cell adhesion (e.g. GJB2), immune response (e.g. IFIH1 and SAMHD1), and ion transport (e.g. CFTR)." (PMID 41546701, 2026). "Additionally, overexpression of CFTR suppresses apoptosis and promotes glioma progression in both subcutaneous and orthotopic xenograft models." (PMID 32463592, 2020). "To determine whether CFTR has channel function in glioma cells, we used patch‐clamp technique to examine CFTR whole‐cell current in SW1088 cells." (PMID 32463592, 2020).